H3C7 (H3 clustered histone 7)
Description:
Core component of nucleosome. Nucleosomes wrap and compact DNA into chromatin, limiting DNA accessibility to the cellular machineries which require DNA as a template. Histones thereby play a central role in transcription regulation, DNA repair, DNA replication and chromosomal stability. DNA accessibility is regulated via a complex set of post-translational modifications of histones, also called histone code, and nucleosome remodeling.
Synonyms: H3FI; HIST1H3F; H3/i
Gene: Protein-coding gene on chromosome 6 (26,250,142 to 26,250,635, reverse strand). Ensembl gene ENSG00000277775.
Subcellular location: Nucleus; Chromosome
Subcellular location (Human Protein Atlas): Nucleoplasm
Pathways (Reactome):
Gene expression (Transcription): B-WICH complex positively regulates rRNA expression; DNA methylation; ERCC6 (CSB) and EHMT2 (G9a) positively regulate rRNA expression; MLL4 and MLL3 complexes regulate expression of PPARG target genes in adipogenesis and hepatic steatosis; NoRC negatively regulates rRNA expression; PRC2 methylates histones and DNA; RNA Polymerase I Promoter Escape; RNA Polymerase I Promoter Opening; RUNX1 regulates genes involved in megakaryocyte differentiation and platelet function; RUNX1 regulates transcription of genes involved in differentiation of HSCs; Regulation of endogenous retroelements by KRAB-ZFP proteins; Regulation of endogenous retroelements by Piwi-interacting RNAs (piRNAs); Regulation of endogenous retroelements by the Human Silencing Hub (HUSH) complex; SIRT1 negatively regulates rRNA expression; Transcriptional regulation by small RNAs
Chromatin organization: CHD1 and CHD2 subfamily; CHD6, CHD7, CHD8, CHD9 subfamily; ChAHP complex assembly; Chromatin modifying enzymes; HATs acetylate histones; HDACs deacetylate histones; HDMs demethylate histones; Interaction of NuRD complexes with transcription factors; NuRD complex assembly; PKMTs methylate histone lysines; RMTs methylate histone arginines
Disease: Defective pyroptosis; Dengue Virus-Host Interactions; HCMV Early Events; HCMV Late Events
Signal Transduction: Activated PKN1 stimulates transcription of AR (androgen receptor) regulated genes KLK2 and KLK3; Estrogen-dependent gene expression; Formation of the beta-catenin:TCF transactivating complex; Pre-NOTCH Transcription and Translation
Developmental Biology: Activation of anterior HOX genes in hindbrain development during early embryogenesis; Chromatin modifications during the maternal to zygotic transition (MZT); Transcriptional regulation of granulopoiesis
Immune System: FXIIa activates plasma kallikrein-kinin system; Interleukin-7 signaling; Regulation of PD-L1(CD274) transcription
and 8 more pathways
Gene Ontology:
Molecular function: cadherin binding; protein binding; structural constituent of chromatin; nucleosomal DNA binding; DNA binding; protein heterodimerization activity
Biological process: epigenetic regulation of gene expression; nucleosome assembly; chromatin organization; heterochromatin formation; telomere organization
Cellular component: chromatin; extracellular exosome; membrane; nucleoplasm; nucleosome; nucleus; protein-containing complex; extracellular region; chromosome
Genetic constraint (gnomAD): Loss-of-function variants: 6 observed, 8.19 expected, observed/expected ratio (o/e) 0.73, 90% interval 0.4 to 1.43. That is too few expected variants to judge how well the gene tolerates losing a copy. Missense variants: 163 observed, 205.66 expected, observed/expected ratio (o/e) 0.79, 90% interval 0.7 to 0.9. Synonymous variants: 113 observed, 83.64 expected, observed/expected ratio (o/e) 1.35, 90% interval 1.16 to 1.58.
Homologues: Orthologues: rat Hist1h2ail1 (100% identical), Drosophila melanogaster His3:CG33812 (99% identical), zebrafish si:ch1073-153i20.2 (99% identical), zebrafish si:ch211-113a14.20 (99% identical), zebrafish si:ch211-113a14.23 (99% identical), zebrafish si:ch211-113a14.27 (99% identical), zebrafish zgc:173552 (99% identical), Caenorhabditis elegans his-17 (97% identical), Caenorhabditis elegans his-2 (97% identical), Caenorhabditis elegans his-32 (97% identical), Caenorhabditis elegans his-40 (97% identical), Caenorhabditis elegans his-42 (97% identical), and 6 more. Paralogues in human: H3C1 (100% identical), H3C10 (100% identical), H3C11 (100% identical), H3C12 (100% identical), H3C2 (100% identical), H3C3 (100% identical), H3C4 (100% identical), H3C6 (100% identical), H3C8 (100% identical), H3C13 (99% identical), H3C14 (99% identical), H3C15 (99% identical), and 8 more.
Diseases named in the same sentence as H3C7 in open-access papers:
H3C7 is named in the same sentence as 1 disease in open-access papers, as found by Europe PMC text mining. Sharing a sentence is not in itself a finding about the gene and the disease. The quoted sentences say what the papers report.
infection (1 paper, 2025). The state of being infected such as from the introduction of a foreign agent such as serum, vaccine, antigenic substance or organism. "The downregulation of Ccl2 and H3c7 in the glycoprotein group suggests impaired leukocyte migration, which may limit the host’s ability to mount the effective immune response at infection sites." (PMID 40552294, 2025).